NF1 (neurofibromin 1)
Diseases named in the same sentence as NF1 in open-access papers (continued):
Sharing a sentence is not in itself a finding about the gene and the disease.
neurofibromatosis type 1 (continued). "We also mapped various pathogenic mutations observed in neurofibromatosis type 1 diseases, which include L1208W, L1211R, D1217G, and deletion of M1215 at the N-terminal end, and L1490P, Q1494R/E, and G1498E at the C-terminal end of the GAPex region in NF1." (PMID 32697994, 2020). "Neurofibromatosis type 1 is caused by mutations within the NF1 gene." (PMID 33121128, 2020). "We used the NF1 variant spectrum, since neurofibromatosis type 1 clinical diagnosis is usually suspected in early years of life when canonical symptoms may not be present or fully developed." (PMID 31979111, 2020). "However, there is a clear association with type 1 neurofibromatosis (NF1), as the prevalence of NF1 in CPT patients exceeds 50%." (PMID 32507071, 2020). "Neurofibromatosis type 1, a disease characterized by benign neurofibromas and malignant tumors of the nervous system, is caused by mutations in the 300-kb tumor suppressor gene, NF1, that encodes the protein neurofibromin." (PMID 31836666, 2020). "Neurofibromatosis type 1 (NF1) is the most frequent hereditary cancer predisposition syndrome and is caused by germline mutations in the NF1 gene encoding for neurofibromin, a very large cytoplasmic protein that functions as a negative regulator of RAS oncoproteins." (PMID 32582540, 2020). "Neurofibromatosis type 1 (NF1) is an autosomal dominant disorder of neural crest-derived tissues that affects approximately 1 in 3500 individuals worldwide and is caused by loss of one functional copy of the NF1 gene on chromosome 17." (PMID 31545171, 2019). "With a birth incidence of approximately 1:3000, Neurofibromatosis type 1 is caused by dominantly inherited mutations in NF1 (MIM 613113), a complex gene encoding for neurofibromin, a GTPase-activating protein that negatively regulates the Ras/MAPK signaling pathway." (PMID 31370276, 2019). "NF1 mutations are mainly found in patients with neurofibromatosis type 1 (NF1)." (PMID 31881853, 2019). "Neurofibromatosis type 1 (NF1) is characterized by an extreme clinical variability both within and between families that cannot be explained solely by the nature of the pathogenic NF1 gene mutations." (PMID 31730495, 2019). "It is believed that neurofibromatosis type 1, associated with an increased risk of gastrointestinal stromal tumors (GISTs) is caused by functionally biallelic losses of the tumor suppressor gene, NF1." (PMID 29966337, 2018). "Heterozygous germline mutation of NF1 results in the genetic disease neurofibromatosis type 1." (PMID 29662612, 2018). "In addition, for patients with neurofibromatosis type 1 (a mutated NF1 gene), intense pulsed-radio frequency (IPL-RF) in combination with topical application of vitamin D3 ointment is one of the current treatments." (PMID 28386563, 2017). "Germline mutations in NF1 gene are associated with Neurofibromatosis type 1." (PMID 27980226, 2017). "Germline mutations of NF1 gene are associated with neurofibromatosis type 1." (PMID 27980226, 2017). "Notably, NF1 germline mutations underlie the neurofibromatosis type 1 phenotype, a disease that is reportedly diagnosed at higher rates in the AJP than in the European population." (PMID 28502252, 2017). "Malignant peripheral nerve sheath tumors or MPNSTs arise in patients with type 1 neurofibromatosis (NF1) and are often associated with activation of the Ras pathway due to loss of function mutations in NF1, a gene which encodes the Ras-GTPase activating protein (GAP), Neurofibromin (NF)." (PMID 29212209, 2017). "In the future, this new strain of mouse will be a useful tool in determining if specific aspects of Neurofibromatosis type I can be attributed to loss of Nf1’s role in Ras-signaling and could therefore be treated by medicines that target this pathway." (PMID 26460546, 2015).
neurofibromatosis type 1 (continued). "Including patients with clinical criteria of Neurofibromatosis type 1 and loss of heterozygosity at the NF1 locus, 41% of the cohort could be associated with genetic aberrations in known genes." (PMID 24466223, 2014). "Neurofibromatosis type 1 is a genetic disorder caused by mutations in the NF1 gene." (PMID 24904277, 2014). "NF1 (von Recklinghausen’s disease) has been associated with an increased risk of MPNST and MTT." (PMID 24527089, 2014). "To examine whether oncogenic GNAQ or GNA11 mutations are required in uveal melanomas bearing NF1 mutations, we examined a uveal melanoma tumor from a patient with neurofibromatosis type 1, which is known to be caused by inherited heterozygous mutations in NF1." (PMID 23555837, 2013). "Neurofibromatosis type-1 (NF1) is caused by mutations of the NF1 gene at 17q11.2." (PMID 23101500, 2012). "Neurofibromatosis type 1 is an autosomal dominant disorder caused by a mutation in the NF1 gene." (PMID 23304574, 2012). "A NM at DNA base 910 ("C" → "T") of NF1 is associated with neurofibromatosis type-I." (PMID 21781308, 2011). "Neurofibromatosis type 1 (NF1) is a multisystemic autosomal dominant genetic disorder primarily marked by loss-of-function mutations in the NF1 gene." (PMID 41399671, 2026). "Neurofibromatosis type 1 (NF1) is a neurogenetic disorder caused by loss-of-function mutations in the gene neurofibromin 1 (NF1)." (PMID 41582719, 2026). "Neurofibromatosis type 1 (NF1) is a multisystemic genetic disorder characterized by NF1 gene mutations." (PMID 41399671, 2026). "Neurofibromatosis type 1 (NF1), which is an autosomal dominant hereditary disorder caused by mutations of the NF1 gene, has an incidence of approximately one in 2,500-5,000 individuals." (PMID 39906425, 2025). "Neurofibromatosis type 1 (NF1) is a rare autosomal dominant neurogenetic disorder caused by heterozygous mutations of the NF1 gene on chromosome 17q11.2 with a prevalence of 1 in 2500 to 3000 individuals." (PMID 40369288, 2025). "Approximately 50% of cases arise in patients with neurofibromatosis type 1 (NF1), an autosomal dominant genetic disorder in which mutations are found in the Neurofibromin 1 gene." (PMID 41272396, 2025). "Neurofibromatosis type 1 (NF1) is an autosomal dominant tumor predisposition syndrome caused by pathogenic variants in the NF1 gene." (PMID 40895107, 2025). "Neurofibromatosis type 1 (NF1) is an autosomal dominant neurocutaneous disorder caused by variants in the NF1 gene, which encodes for neurofibromin, a RAS GTPase-activating protein that negatively regulates the MAPK/MEK pathway." (PMID 40900834, 2025). "Neurofibromatosis Type 1 (NF1) is an autosomal dominant genetic disorder caused by heterogeneous mutations in the tumor suppressor gene NF1." (PMID 41256734, 2025). "Neurofibromatosis type 1 (NF1) is an inherited multisystem disorder caused by dominant loss-of-function mutations of the tumor-suppressor gene neurofibromin 1, which is located at 17q11.2.1." (PMID 38170086, 2024). "Neurofibromatosis type 1 (NF1) is a genetic condition caused by a hereditary deletion mutation of the NF1 gene on chromosome 17q11.2." (PMID 39835036, 2024). "Over 20% of patients with neurofibromatosis type 1 syndrome (NF1) have a nonsense mutation in the NF1 gene." (PMID 37520682, 2023). "Neurofibromatosis type 1 (NF1) is a complex neurocutaneous condition caused by pathogenic variants in the NF1 gene (OMIM ∗ 613113) and characterized by a heterogeneous clinical presentation." (PMID 40225171, 2023). "Neurofibromatosis type 1 (NF1) is an autosomal dominant condition caused by inactivating variants in the NF1 gene." (PMID 37238595, 2023). "Neurofibromatosis type 1 (NF1) is a clinical heterogeneous neurocutaneous syndrome caused by pathogenic variants in the NF1 gene." (PMID 36923276, 2023). "Neurofibromatosis type 1 (NF1) is a neurocutaneous syndrome caused by pathogenic variants in the NF1 gene, encoding a multidomain inhibitor of Ras activity." (PMID 36923276, 2023).
neurofibromatosis type 1 (continued). "Neurofibromatosis type 1 (NF1) is an autosomal dominant disorder caused by inherited or spontaneous mutations in the NF1 gene, which encodes neurofibromin." (PMID 37123679, 2023). "It is believed that a combination of acquired physical and germline NF1 tumor silencer quality modifications causes CA to develop in neurofibromatosis type 1 (NF1) acquired malignancy inclination condition." (PMID 37675821, 2023). "Neurofibromatosis type 1 (NF1) is an autosomal dominant genetic trait due to an inherited heterozygous mutation of the NF1 gene." (PMID 37627552, 2023). "In addition, type 1 neurofibromatosis (NF1), resulting from a loss-of-function mutation in the NF1 gene, may be related to multifocal GIST, predominantly located in the jejunum or ileum, with the frequent presentation of gastrointestinal bleeding and anemia." (PMID 35740497, 2022). "Neurofibromatosis type 1 (NF1) is one of the most common genetic tumor predisposition syndrome, caused by mutations in the NF1." (PMID 35885913, 2022). "Germline mutations of NF1 cause neurofibromatosis type 1 (NF1), which is characterized by multiple benign peripheral nerve sheath tumors known as neurofibromas." (PMID 35625983, 2022). "Neurofibromatosis type 1 (NF1) is a rare autosomal dominant disorder with an incidence of one case per 3000 caused by germline pathogenic variants in the NF1 tumour suppressor gene." (PMID 35597953, 2022). "Neurofibromatosis type 1 (NF1) is a dominant hereditary disease characterized by the mutation of the NF1 gene, affecting 1/3000 individuals worldwide." (PMID 35677169, 2022). "Neurofibromatosis type 1 (NF1) is a neurocutaneous syndrome, due to heterozygous pathogenic variants in NF1 gene." (PMID 36411470, 2022). "Neurofibromatosis type 1 (NF1) is a proteiform genetic condition caused by pathogenic variants in NF1 and characterized by a heterogeneous phenotypic presentation." (PMID 33919865, 2021). "Neurofibromatosis type 1 (NF1) is an autosomal dominant neuroectodermal disorder caused by heterozygous loss-of-function mutations of the tumour suppressor gene NF1 on chromosome 17q11.2." (PMID 33842116, 2021). "Germline inactivating mutations of NF1 also occur in individuals with the familial tumor susceptibility syndrome Neurofibromatosis Type 1 (NF1)." (PMID 34530870, 2021). "Neurofibromatosis type 1 (NF1) is an autosomal dominant genetic disorder with almost 3000 different disease-causing variants within the NF1 gene identified." (PMID 34945792, 2021). "Neurofibromatosis type 1 (NF1), a genetic disease, is caused by a novel germline mutation on the NF1 gene or hereditary transmission of NF1 mutations." (PMID 34948100, 2021). "Linkage studies showed that loss‐of‐function mutations in the NF1 gene are causative of Neurofibromatosis type 1(NF1) (OMIM 162200), which is an autosomal dominant inherited disease and characterized by evolving tumors and nontumor manifestations." (PMID 33764694, 2021). "Neurofibromatosis Type 1 (NF1) is an autosomal dominant disease that is caused by loss of function-mutations and/or deletions in the tumour suppressor gene neurofibromin 1 (NF1)." (PMID 32102484, 2020). "Neurofibromatosis Type 1 (NF1) is the most common autosomal dominant neurocutaneous disease, caused by mutations in the NF1 tumor suppressor gene, located in a region on chromosome 17ql1.2." (PMID 31053133, 2019). "Neurofibromatosis type 1 (NF1) is an autosomal dominant disorder caused by loss of function mutations in NF1 gene, which occurs in approximately 1 of 3000 births." (PMID 31234911, 2019). "Moreover, we also report, for the first time, the frameshift mutation [c.7686delG (p.Ile2563fsX40)] in the NF1 gene, as well as its association with type 1 neurofibromatosis (NF1), characterized by pigmentary lesions (café au lait spots, Lisch nodules, freckling) and cutaneous neurofibromas." (PMID 30828344, 2019).
neurofibromatosis type 1 (continued). "Multiple cutaneous neurofibromas (cNF) are characteristic of neurofibromatosis type 1 (NF1) patients who have an autosomal dominant loss-of-function mutation of an NF1 allele." (PMID 31107888, 2019). "Neurofibromatosis type 1 (NF1) is a dominantly inherited Rasopathy caused by mutations in the NF1 gene on chromosome 17." (PMID 29335026, 2018). "Germline mutations in NF1 lead to a genetic syndrome called neurofibromatosis type 1 (NF1), a relatively frequent genetic condition with an incidence of 1 in 3,000, resulting in a higher predisposition to multiple tumors arising from various cell types." (PMID 29276510, 2017). "Since many OPGs occur in the context of the Neurofibromatosis Type 1 (NF1) cancer predisposition syndrome, we have previously employed Nf1 genetically-engineered mouse (GEM) strains to study the pathogenesis of these low-grade glial neoplasms." (PMID 28525381, 2017). "Neurofibromatosis type 1 (NF1) is a rare hereditary tumor predisposition syndrome caused by a germline mutation in the NF1 tumor suppressor gene." (PMID 26625155, 2015). "Neurofibromatosis type 1 (NF1) is an autosomal dominant disease caused by mutations in the NF1 tumor suppressor gene, which affect approximately 1 out of 3000 individuals." (PMID 26039236, 2015). "Neurofibromatosis type 1 (NF1) caused by NF1 gene mutation is a commonly inherited autosomal dominant disorder." (PMID 25109740, 2014). "Neurofibromatosis type 1 (von Recklinghausen’s disease-NF1) is caused by an alteration of the NF1 gene, a tumor suppressor located on the long arm of chromosome 17 (17q11.2)." (PMID 24708790, 2014). "Persons affected by neurofibromatosis type 1 (NF1) have a decreased survival, yet information on NF1-associated mortality is limited." (PMID 21439034, 2011). "Persons with neurofibromatosis type 1 (NF1) exhibit enhanced glucose metabolism, which is replicated in Nf1-mutant mice." (PMID 40279245, 2025). "They encompass a broad range of conditions, including neurofibromatosis type 1 (NF1), neurofibromatosis type 2 (NF2), tuberous sclerosis complex, Sturge–Weber syndrome, von Hippel–Lindau disease, and others." (PMID 40843672, 2025). "Three patients with PGPVs of NF1 had already been diagnosed as neurofibromatosis type 1 by their phenotypes and family history." (PMID 40755265, 2025). "Trametinib, a MEK inhibitor, has demonstrated activity in tumors with NF1 alteration in preclinical models, and clinical activity in low-grade glioma and plexiform neurofibromas in neurofibromatosis type 1." (PMID 41170454, 2025). "Type 1 neurofibromatosis (NF1) is an autosomal dominant disorder including a tumor suppressor gene, neurofibromin 1, located on 17q11.2, which encodes a GTPase-activating protein involved in the RAS/MAPK pathway." (PMID 40002695, 2025). "The fifth germline alteration was an NF1 deletion in a patient with neurofibromatosis type 1 and osteosarcoma." (PMID 39794422, 2025). "Neurofibromatosis type 1, also known as Von Recklinghausen disease, is a multisystemic autosomal dominant disorder caused by variants in theNF1gene (OMIM 613113,neurofibromin 1).3While family history is common, ∼ 50% of cases result from de novo variants." (PMID 40562378, 2025). "Neurofibromatosis type I (NF1, OMIM 162200) is an autosomal dominant multisystemic disorder caused by loss of function mutations in the NF1 gene, located at chromosome 17q11.2." (PMID 40133996, 2025). "Germline PVs in NF1 lead to neurofibromatosis type I, a disorder characterized by fibromatous tumors and café-au-lait spots and individuals with this disorder have an increased susceptibility to develop malignant and benign tumors (OMIM: 162200)." (PMID 39979679, 2025). "Neurofibromatosis Type 1 (NF1) arises from mutations in the NF1 gene situated on chromosome 17." (PMID 40764996, 2025).
neurofibromatosis type 1 (continued). "Background/Objectives: This study presents the first molecular characterization of NF1 gene variants in Kazakhstani patients, expanding regional understanding of neurofibromatosis type 1 (NF1)." (PMID 41300842, 2025). "Plexiform neurofibromas are peripheral nerve sheath tumors that occur almost exclusively in children with Neurofibromatosis type I (von Recklinghausen disease; NF-1) and often manifest by early childhood." (PMID 39729290, 2025). "It is clinically divided into several subtypes, with the 2 most common subtypes being neurofibromatosis type 1 (NF1) and NF2." (PMID 40153767, 2025). "An example is neurofibromatosis type-1 (NF1), where patients have a germline alteration in NF1, and tumors are thought to form with a second somatic mutation leading to inactivation of the NF1 protein." (PMID 40422539, 2025). "Sixty-seven patients (8.1%) had documented CPS, with the most prevalent being neurofibromatosis type 1 (NF-1; N=25), followed by tuberous sclerosis (N=10), neurofibromatosis type 2 (NF-2; N=7), and Li-Fraumeni syndrome (N=7)." (PMID 39974082, 2025). "Neurofibromatosis Type 1 (NF1, OMIM #162200) is an autosomal dominant genetic disorder caused by pathogenic variants in the NF1 gene (NCBI Gene ID 4763), which encodes the tumor suppressor protein neurofibromin." (PMID 40940846, 2025). "Neurofibromatosis type 1 (NF1) is one of the most common genetic diseases, affecting 1 in 3000 births, caused by heterogeneous mutations in the tumor suppressor gene NF1." (PMID 41256734, 2025). "Neurofibromatosis type 1 (NF1) is a genetic disorder transmitted in a dominant fashion due to mutations in the NF1 gene, responsible for the production of the tumor suppressor neurofibromin." (PMID 39612400, 2024). "Neurofibromatosis type 1 (NF1), is a common autosomal dominant genetic disorder characterised by mutations in the NF1 gene on chromosome 17." (PMID 39655114, 2024). "The remainder are attributed to various causes, including vasculitis, connective tissue disease, and neurofibromatosis type 1 (NF-1)." (PMID 39210188, 2024). "NF1, also recognized as von Recklinghausen disease, is one of the most prevalent autosomal dominant single-gene neurocutaneous disorders." (PMID 39542941, 2024). "Schwann cell tumors are the most common cancers of the peripheral nervous system and can arise in patients with neurofibromatosis type-1 (NF-1) or neurofibromatosis type-2 (NF-2)." (PMID 38216572, 2024). "Neurofibromatosis type 1 (NF1) (OMIM#162200) is an autosomal dominant multi-symptomatic disorder affecting ~1 in 2000–3000 individuals worldwide and is caused by inherited or de novo mutations in the NF1 tumor suppressor gene (chromosome 17q11.2)." (PMID 38667335, 2024). "Neurofibromatosis type 1 (NF1) is defined from a genetic perspective as an inherited or non-inherited disease caused in the first case by an autosomal dominant mutation in the NF1 gene, which has a tumor-suppressive function." (PMID 38364341, 2024). "Classical NF1 is a common autosomal dominant disorder (Von Recklinghausen Disease; OMIM #162200) affecting at least one in 3000 births worldwide." (PMID 39355740, 2024). "Neurofibromatosis type 1 (NF1) is an autosomal-dominant genetic disorder caused by loss of expression of the neurofibromin (Nf1 gene product) tumor suppressor gene on chromosome 17 and subsequent dysregulation of RAS/mitogen-activated protein kinase (MAPK) signaling in Schwann cells (SCs)." (PMID 39061138, 2024). "Neurofibromatosis type 1 and 2 (NF1, NF2) and schwannomatosis make up the global spectrum of neurofibromatosis." (PMID 38603731, 2024). "Plexiform neurofibromas in neurofibromatosis type 1 (pNF1), characterized by aggressive growth and local invasiveness, are comprised primarily of Schwann cell-derived tumor cells (Nf1−/−) and the tumor microenvironment (TME)." (PMID 39061138, 2024).